CDK16 (cyclin dependent kinase 16)
Diseases named in the same sentence as CDK16 in open-access papers (continued):
Sharing a sentence is not in itself a finding about the gene and the disease.
cancer (continued). "For the inferred perturbed miR-125 regulatory networks, there are only three common targets (CDK16, TOMM40 and KIAA1522), which suggests that miR-125 may regulate different pathways in the two types of cancers." (PMID 24278370, 2013). "Moreover, CDK16 inhibition downregulated MYC and PD‐L1 in NSCLC cells, suggesting that the enhanced antitumor immune response may be a downstream effect of inducing cancer cell senescence to exercise its tumor‐suppressive function." (PMID 34687270, 2022). "However, the mechanism by which CDK16 is involved in cancer cell growth is unknown and selective small-molecule inhibitors for CDK16 have not been identified." (PMID 28057719, 2017). "The 3’UTR of several hallmark genes such as Cyclin-dependent kinase 2 (CDK2), Cyclin-dependent kinase 16 (CDK16), MAPK1 and NFKBIL1 are significantly longer in HPV positive cancer compared with HPV negative cancer." (PMID 31039132, 2019).
tumor (23 papers, 2014 to 2025). "Previous research has shown that high CDK16 expression is associated with tumor growth and infiltration, consistent with our findings." (PMID 38261737, 2024). "In vivo, in various tumor models, CDK16 deficiency significantly suppressed tumor growth and metastasis of TNBC, while CDK16 overexpression remarkably promoted metastasis of TNBC." (PMID 35449080, 2022). "CCNY, the key cyclin binding partner responsible for activating CDK16, has been shown to influence cell proliferation and tumor progression in NSCLC." (PMID 40665337, 2025). "To validate these observations, we further examined the Tumor Microenvironment (TME)-related pathways influenced by CDK16." (PMID 38261737, 2024). "In our study, we harnessed the advanced data analysis tools provided by cBioPortal to scrutinize the genetic alterations specific to CDK16 across a range of tumor types." (PMID 38261737, 2024). "Mechanistically, CDK16 mRNA acts as a sponge to bind and inactivate miR-324-5p, inhibiting its tumor-suppressive activity in hepatocellular carcinoma and melanoma cells." (PMID 38951876, 2024). "This encompasses both innate and adaptive immune systems, highlighting a versatile role of CDK16 in modulating the immune response within the tumor microenvironment." (PMID 38261737, 2024). "Our results highlight a strong link between increased CDK16 expression and an immunosuppressive tumor microenvironment, implying CDK16’s role in tumor-induced immunosuppression and potential implications for immune therapy." (PMID 38261737, 2024). "Despite its significance, the influence of CDK16 on the tumor microenvironment, particularly its correlation with immune therapies, has been historically overlooked." (PMID 38261737, 2024). "The pharmacological inhibition of rebastinib on CDK16 also achieved encouraging anti-tumor efficiency in TNBC." (PMID 35449080, 2022). "Both genetic knockdown and pharmacological inhibition of CDK16 significantly suppress the tumor progression of TNBC." (PMID 35449080, 2022). "Pharmacological inhibition of CDK16 was achieved by the small molecular inhibitor rebastinib to further assess the anti-tumor utility of targeting CDK16." (PMID 35449080, 2022). "Nevertheless, the compatible anti-tumor activity produced by the inhibition of Tie2 and CDK16 further establishes the value of rebastinib as an effective anti-tumor compound." (PMID 35449080, 2022). "Either genetic depletion or pharmacological inhibition of CDK16 effectively suppresses tumor growth and metastasis of TNBC in various tumor models." (PMID 35449080, 2022). "CDK16 knockdown dramatically delayed tumor formation and suppressed tumor growth in the MDA-MB-231 tumor xenograft model, as indicated by reduced tumor volume, mass, and size in the CDK16-KD group compared to that in the control group." (PMID 35449080, 2022). "With the exception of CDK16, other CDKs probably participate in and regulate immune cell infiltration into the tumor microenvironment." (PMID 35814446, 2022). "To test this possibility, we constructed an MDA-MB-231 stable line overexpressing CDK16 (CDK16-OE), and labeled it with a luciferase reporter gene to quantitatively monitor tumor metastasis in vivo by bioluminescence imaging (BLI)." (PMID 35449080, 2022). "The elevated expression of CDK16 correlates positively with the tumor aggressiveness and is required for tumor cell proliferation." (PMID 32098961, 2020). "For CDK16 several studies described a significant upregulation of this kinase in different tumor entities compared to adjacent normal tissue." (PMID 32098961, 2020). "In tumor xenografts of cutaneous SCC cells, the inducible conditional knockdown of Cdk16 suppressed tumor growth." (PMID 29629337, 2018). "Moreover, CDK16 overexpression contributes to an immunosuppressive tumor microenvironment, extensively suppressing immune-related features such as the expression of immune-related genes and pathways, as well as the count of immune-infiltrating cells." (PMID 38261737, 2024).
tumor (continued). "This suggests that CDK16 may affect immune cell infiltration in the tumor microenvironment, influencing immune responses." (PMID 38261737, 2024). "Consequently, we proceeded to delve deeper into the mechanistic action of CDK16 in the Tumor Immune Microenvironment (TIME)." (PMID 38261737, 2024). "Gene amplification and mutation were identified as the primary types of genetic alterations in CDK16, which may be related to tumor development and treatment response." (PMID 38261737, 2024). "Moreover, CDK16 can promote tumor progression by regulating the mammalian target of rapamycin (mTOR) pathway." (PMID 34687270, 2022). "Finally, genes involved in cell cycle regulation and tumor growth like CDK16, CDC20 and the Ras homologue enriched in brain (RHEB) were ubiquitously expressed in our established CSCs." (PMID 33800955, 2021). "Altogether, this study demonstrated that circ_1306 could alleviate the inhibition effect of miR‐584‐5p on the expression of CDK16 by sponging miR‐584‐5p, thus promoting the tumour growth by inducing cell proliferation and reducing cell apoptosis." (PMID 33135290, 2020). "In vivo, overexpression of miR‐584‐5p or knockdown of circ_1306 could inhibit the expression of CDK16, and suppress tumour growth." (PMID 33135290, 2020). "Treatment with Cdk16 siRNA-LNP reduced tumor volume and weight significantly." (PMID 29629337, 2018). "These genetic alterations may lead to abnormal CDK16 activity, promoting tumor growth." (PMID 38261737, 2024). "Furthermore, CDK16 may also represent a potential therapeutic target for specific tumor types that currently lack effective management strategies, as recently proposed." (PMID 38951876, 2024). "Targeting CDK16 and Tie2 may jointly promote the anti-tumor activity of rebastinib in TNBC." (PMID 35449080, 2022). "Reb has been identified as an anti-tumor drug and an antagonist of CDK16 that functions by disrupting the CCNY-CDK16 interaction." (PMID 40665337, 2025). "The implications of such involvement are twofold: firstly, CDK16’s influence on the immune system may contribute to the immune evasion strategies employed by tumors; secondly, it suggests potential therapeutic targets within these pathways that could be exploited to enhance anti-tumor immunity." (PMID 38261737, 2024). "Together, these results demonstrated that pharmacological inhibition of CDK16 effectively suppresses tumor growth and metastasis of TNBC, supporting CDK16 as a promising target for the treatment of TNBC." (PMID 35449080, 2022). "The results of the PDX model further verified the anti-tumor effect of targeting CDK16 in TNBC, which significantly delayed tumor occurrence, suppressed tumor growth, and finally inhibited tumor progression." (PMID 35449080, 2022). "Our study supports CDK16 as a potential therapeutic target for TNBC and provides evidence and guidance for developing CDK16 inhibitors as anti-tumor agents." (PMID 35449080, 2022). "CDK16 can improve the proliferation and migration ability of TNBC cells in vitro, and promote tumor growth and metastasis of TNBC in vivo." (PMID 35449080, 2022). "To verify the expression of CDK16 protein, we performed immunohistochemical (IHC) analysis using a tissue microarray containing 50 TNBC tumor tissues and four adjacent tissues." (PMID 35449080, 2022). "Therefore, our study expands the understanding of PRC1 function and provides an alternative tumor therapy strategy: inhibiting PRC1 by targeting its regulatory kinase, CDK16." (PMID 35449080, 2022). "We collected additional six cases of clinical TNBC tumor samples and an equal number of non-cancerous samples, and examined the protein expression of CDK16 by immunoblot analysis." (PMID 35449080, 2022). "For example, niraparib and rucaparib have also been found to inhibit some kinases including DYRK15, CDK16 and PIM3 that may be therapeutically useful if these kinases are aberrantly expressed in specific tumours." (PMID 34445211, 2021).
CDK16 also shares sentences with these, for which no sentence is quoted: acute myeloid leukemia (2 papers); microcephaly (2); asthenozoospermia (1); autism spectrum disorder (1); benign melanocytic nevus (1); colon adenocarcinoma (1); colorectal adenocarcinoma (1); endometrial cancer (1); glioblastoma (1); Infertility (1); lung adenocarcinoma (1); lung squamous cell carcinoma (1); medulloblastoma (1); melanocytic nevus (1); nasopharyngeal carcinoma (1); non-small cell lung carcinoma (1); ovarian tumor (1); papilloma (1); prostate adenocarcinoma (1); synucleinopathy (1); testicular germ cell tumor (1); Thyroid Carcinoma (1); triple-negative breast carcinoma (1).